WNT1 (Wnt family member 1)
Diseases named in the same sentence as WNT1 in open-access papers (continued):
Sharing a sentence is not in itself a finding about the gene and the disease.
gastric cancer (34 papers, 2009 to 2024). A primary or metastatic malignant neoplasm involving the stomach. "In addition to mutations in Wnt signaling, the overexpression of Wnt1 and Wnt6 has been observed in gastric cancer." (PMID 37190019, 2023). "Indeed, different components of the Wnt pathway have been shown to be mutated or dysregulated in gastric cancer, including Wnt1, SFRPs, Axin1 and Axin2, APC, GSK3-β, and β-catenin." (PMID 28230774, 2017). "miR-132–3p and miR-140–5p can reduce the expression of WNT1 and inhibit gastric cancer cell proliferation and invasion; miR-491–5p can target and silence Wnt3a, inhibit the proliferation of gastric cancer cells and induce apoptosis." (PMID 38952556, 2024). "It has been suggested that WNT1 is involved in gastric cancer progression and the induction of immune tolerance." (PMID 38952556, 2024). "The overexpression of Wnt1 or a combination of prostaglandin pathways induces preneoplastic lesions or invasive gastric cancer, respectively, in mouse models." (PMID 37190019, 2023). "The lncRNA DLGAP1-AS1 has been demonstrated to increase Wnt1 transcription and gastric cancer growth by interacting with Six3." (PMID 35178091, 2022). "It was reported that si-FOXF2 stimulated WNT1 and β-catenin and further upregulated the Wnt target genes cyclin D and c-myc in a gastric cancer cell line." (PMID 33176855, 2020). "Such as, microRNA-140-5p suppresses cell proliferation and invasion in gastric cancer by targeting WNT1 in the WNT/β-catenin signaling pathway." (PMID 31249473, 2019). "It has also been shown that Notch4 promotes gastric cancer growth through activation of Wnt1/β-catenin signaling." (PMID 27435629, 2016). "Recently, miR-200b and miR-22 have been shown to synergistically suppress Wnt-1 in gastric cancer, indicating an additive effect of miRNAs in modulating gene expression via a fine-tuning manner." (PMID 25825983, 2015). "In this study, we confirmed the inhibition of AGS gastric cancer cell migration by downregulating the Wnt-1 signaling pathway via Cf-GP." (PMID 23982808, 2013). "Wnt1 showed differential expression profiles between normal, tumor and metastatic tissues and its deregulation affected survival outcome in patients with lung and gastric cancer." (PMID 36056132, 2022). "In addition, a recent study reported that DLGAP1-AS2 binds to the transcription factor Six3 and inhibits its occupancy in Wnt1 promoter, resulting in the activation of Wnt/β-catenin signaling in gastric cancer cells." (PMID 36376892, 2022). "Notch4 activates Wnt1/β-catenin signaling to accelerate gastric cancer growth." (PMID 28881855, 2017). "In addition, Notch4 activation induced expression and activation of Wnt1, β-catenin and downstream target genes, c-Myc and cyclin D1, in gastric cancer cells, while Notch4 inhibition had opposite effects." (PMID 27363496, 2016). "Finally, we demonstrated that heterozygous deletion of the SLD5 gene attenuated tumor progression in a murine spontaneous gastric cancer model using the Wnt1/C2mE transgenic mouse." (PMID 24244394, 2013). "Emerging evidence has demonstrated that Wnt/β‐catenin is activated after gastric cancer and plays a critical role in promoting invasion and migration through overexpressing or increasing the functions of several components of the Wnt pathway such as Wnt1, Wnt2, Wnt3, Wnt5a, Fzd‐3, CTNNB1 and LRP6." (PMID 28994231, 2018). "In addition, Wnt-1 was related to CD44 expression, while inhibition of the Wnt/β-catenin pathway suppressed gastric cancer stem cells." (PMID 30884828, 2019). "In addition, we show that human gastric cancer cells AGS, which primarily express the Wnt ligand Wnt1, process paracrine Wnt signaling via cytonemes, which are influenced by Ror2 signaling." (PMID 30060804, 2018).
gastric cancer (continued). "In conclusion, we propose that GRA inhibited the initiation and progression of gastric cancer by ameliorating the inflammatory microenvironment through inhibition of COX-2 expression, and by decreasing Wnt-1 expression through the upregulation of tumor suppressor miR-149-3p." (PMID 27713126, 2016). "WNT1 is involved in the maintenance and proliferation of GCSCs through the classical Wnt pathway, and WNT5A is involved in the initiation of the EMT and gastric cancer stem cell proliferation through the nonclassical Wnt pathway." (PMID 38952556, 2024).
osteogenesis imperfecta (33 papers, 2014 to 2025). Osteogenesis imperfecta (OI) comprises a heterogeneous group of genetic disorders characterized by increased bone fragility, low bone mass, and susceptibility to bone fractures with variable severity. "Earlier studies have established that biallelic WNT1 variants cause Osteogenesis Imperfecta Type XV characterized by multiple fractures at a very young age, bone deformities, and extraskeletal manifestations of OI." (PMID 41128774, 2025). "Osteogenesis Imperfecta (OI) is a genetic bone disease caused by mutations in Wnt1 that is characterized by an early onset of osteoporosis with increased bone fragility and reduced bone mass." (PMID 35600583, 2022). "The recent identification of homozygous WNT1 mutations in individuals with osteogenesis imperfecta type XV (OI-XV) has suggested that WNT1 is a key ligand promoting the differentiation and function of bone-forming osteoblasts." (PMID 34759273, 2021). "Mutations in WNT10B have been linked to limb defects and dental abnormalities, and mutations in WNT1 are associated with osteogenesis imperfecta." (PMID 34450027, 2021). "Loss-of-function mutations in WNT1 lead to moderately severe and progressive forms of osteogenesis imperfecta." (PMID 32733380, 2020). "The consequence of disturbed Wnt signaling in osteocytes is demonstrated by a mutation in the WNT1 gene, which causes autosomal-recessive osteogenesis imperfecta, a childhood rare bone disease." (PMID 32733380, 2020). "In 2013, several groups identified WNT1 as a key ligand to the WNT pathway in bone; heterozygous WNT1 mutations were reported to cause autosomal dominant osteoporosis, and homozygous mutations, a more severe osteogenesis imperfecta." (PMID 30858824, 2019). "We report a novel mutation G324C in WNT1 gene responsible for severe recessively inherited Osteogenesis Imperfecta." (PMID 30447692, 2018). "Homozygous mutations in WNT1 cause severe bone fragility known as osteogenesis imperfecta type XV." (PMID 36004351, 2022). "Pyott S.M., Tran T.T., Leistritz D.F., Pepin M.G., Mendelsohn N.J.,Temme R.T., Fernandez B.A., Elsayed S.M., Elsobky E., Verma I.,Nair S., Turner E.H., Smith J.D., Jarvik G.P., Byers P.H. WNT1 mutationsin families affected by moderately severe and progressiverecessive osteogenesis imperfecta." (PMID 33659802, 2020). "Therefore, romosozumab might be beneficial to treat rare bone disease patients with low bone mass phenotypes, such as osteogenesis imperfecta, Wnt1 mutation, and PLS3 mutation." (PMID 32733380, 2020). "The treatment of the Wnt1-related osteogenesis imperfecta mouse model Wnt1sw/sw with anti-sclerostin antibodies did not completely rescue their osteoporotic phenotype." (PMID 39283365, 2025).
lung cancer (31 papers, 2010 to 2025). A malignant neoplasm involving the lung. "In lung cancer, dysregulation of Wnt signaling has been found, and overexpression of Wnt proteins (Wnt1 and Wnt5a) was notably linked to unfavorable overall survival in lung cancer patients." (PMID 31775307, 2019). "Our prior meta-analysis demonstrated that the overexpression of Wnt proteins (Wnt1 and Wnt5a) was notably linked to unfavorable overall survival in lung cancer patients." (PMID 28646916, 2017). "Recently, in a meta-analysis, higher Wnt1 expression was also associated with poorer overall survival in lung cancer patients." (PMID 28199399, 2017). "Restoration of SMARCA4 was associated with decreased lung cancer cell proliferation, metastasis, and epithelial–mesenchymal transition, an effect attributed to its positive regulatory role in the expression of miR-148b, which inhibits the WNT1/β-catenin signaling pathway." (PMID 39888726, 2025). "Furthermore, whether EGFR/ERK1/ERK2 or WNT1/WNT5A/WNT7B gene expression was potentially associated with the OS of lung cancer patients was assessed by Kaplan-Meier curve and Log-rank test." (PMID 34122668, 2021). "It was found that aspirin treatment induced the expression of miR-98, depressing WNT1 in lung cancer cells." (PMID 38872210, 2024). "Its expression level was increased in lung cancer, prostate cancer, and cervical cancer, elevated WNT1 expression was also detected in over 1/3 of NSCLC cases, and was positively correlated with the expression levels of β-catenin, Cyclin D1, and c-Myc." (PMID 37486552, 2023). "MiR-34a-5p/miR-34c-5p/miR-302b-3p —LEF1—CCND1/WNT1/MYC axismay be a key mechanism in inhibition of lung cancer metastasis." (PMID 37191432, 2023). "In lung cancer tissues, WNT1 expression showed an inverse correlation with the proportion of tumor infiltrating cytotoxic T lymphocytes (CTLs)." (PMID 36982422, 2023). "Recently, some studies even found that WNT1 contributes to the pathogenesis of lung cancer by regulating the tumor immune microenvironment." (PMID 37486552, 2023). "In conclusion, WNT1 promotes the pathogenesis of lung cancer, and inhibition of its overexpression by appropriate methods has a potential therapeutic effect on this disease." (PMID 37486552, 2023). "Knockdown of WNT1 in a lung cancer xenograft mouse model led to an increased proportion of antigen specific CTLs in a lung cancer xenograft mouse model." (PMID 36982422, 2023). "In human lung cancer, the main Wnt ligands are Wnt1, Wnt2, Wnt5a, and Wnt7a, and an increase in Wnt proteins, Wnt1 or Wnt5a alone, is significantly related to poor prognosis in NSCLC." (PMID 35719973, 2022). "The gene expression of SOX2 is highly expressed in NSCLC subtypes, and the inhibition of Sox2 downregulates Wnt1/2 and c-myc gene expression, induces cell apoptosis, and reduces metastatic potential in lung cancer." (PMID 33302540, 2020). "And knocking down of Wnt-1 by siRNA had the similar effect of miRNA-148a overexpression on cell migration and invasion in lung cancer cells." (PMID 28199399, 2017). "In conclusion, our studies suggest that miRNA-148a is significantly correlated with tumor progression and poor clinical outcome and can inhibit the migration and invasion of lung cancer cells by directly targeting Wnt1." (PMID 28199399, 2017). "Taken together, our results suggest that miRNA-148a can suppress the migration and invasion of lung cancer cells by targeting Wnt1 and this will provide a new insight into the molecular mechanisms underlying cancer progression in NSCLC." (PMID 28199399, 2017). "Several upstream components of the Wnt pathway have been previously reported to be dysregulated in lung cancer; for example, Wnt-1 and -2 were found to be upregulated in NCSLC cell lines and primary tissues." (PMID 24348855, 2014).
lung cancer (continued). "Wnt1 monoclonal antibodies induce apoptosis of cancer cells in vitro (lung, breast, and mesothelioma cell lines) and in vivo (injection of lung cancer cells into nude mice, treated by Wnt1 antibodies)." (PMID 24212796, 2011). "In lung cancer cells, aspirin activated miR-98, which decreased WNT1 expression." (PMID 38872210, 2024). "In different mouse models of lung cancer, for instance, an efficient silencing of WNT1 in tumors through administration of siWNT1 nanoparticles could be demonstrated, which coincided with a lower tumor burden." (PMID 36982422, 2023). "To explore whether miRNA-148a suppresses metastasis of lung cancer cells through deregulating Wnt1, we studied the effects of silencing Wnt1 on the metastasis of lung cancer cells." (PMID 28199399, 2017). "In conclusion, our results suggest that miRNA-148a inhibited cell migration and invasion through targeting Wnt1 and this might provide a new insight into the molecular mechanisms of lung cancer metastasis." (PMID 28199399, 2017). "Our results also showed that miRNA-148a could inhibit the migration and invasion of lung cancer cells by directly targeting Wnt1." (PMID 28199399, 2017). "Moreover, immunoblotting analysis of the SJ26-treated lung cancer H1299 cells showed that the Wnt1 protein levels were greatly decreased by SJ26 treatment at a dose as low as 1 μM." (PMID 27626678, 2016). "A specific study found that aspirin could improve lung cancer by targeting the miR-98/WNT1 axis." (PMID 38872210, 2024). "miR-939 regulates a large number of genes, such as WNT1, NTSR1, POLK, WWOX and SPN, that are related to lung cancer." (PMID 29228624, 2017). "Several Wnt proteins are differentially expressed in non–small cell lung cancer (NSCLC) specimens, for instance, WNT1 is overexpressed in NSCLC samples, and cancer cells expressing WNT1 are resistant to apoptotic therapies." (PMID 27686331, 2016). "Wnt1 is involved in the regulation of MMP-7 expression, and therefore, Wnt signaling pathway plays a significant role in the lung cancers." (PMID 25588786, 2015). "Our results thus far demonstrate that SOX2 regulates the transcriptional network of oncogenes, including WNT1, WNT2, NOTCH1 and c-MYC and promotes the tumorigenesis of human lung cancer cells." (PMID 22615765, 2012). "In this regard, our results demonstrated that silencing of SOX2 significantly reduces the protein expression level of oncogenes-WNT1, WNT2, c-MYC and NOTCH1 in human lung cancer and further revealed other target cancer genes of SOX2." (PMID 22615765, 2012). "For example, differential expression of several WNT components including WNT1, WNT2, WNT7A, DVL3, β-CATENIN and APC, have been reported in normal lung tissues and lung cancers, particularly in NSCLC (non-small cell lung cancer)." (PMID 22846383, 2012). "In the present study, we found that miRNA-148a inhibited Wnt1 protein expression in lung cancer cells and the expression of miRNA-148a was inversely related to the expression of Wnt1 in both lung cancer and their corresponding adjacent non-tumor lung tissues." (PMID 28199399, 2017). "In addition, higher expression of the oncogenes c-MYC, WNT1, WNT2 and NOTCH1 was detected in side population (SP) cells than in non-side population (NSP) cells of A549 lung cancer cells, indicating a possible mechanism for the tumorigenic potential of CSC’s." (PMID 23349823, 2013).
breast tumors (28 papers, 2005 to 2023). "Accordingly, the analysis of luminal breast tumors from the TCGA database also revealed that WNT1 promoter hypermethylation was associated with a downregulation of its gene expression in primary tumors, suggesting that WNT1 is epigenetically regulated in luminal BC." (PMID 36393855, 2022). "Through enhancing PI3K/AKT/mTOR pathway signaling and β‐catenin activity, GPNMB promotes breast tumor initiation and growth mediated by Wnt‐1 signaling." (PMID 38140790, 2023). "The methylation levels of WNT1 were significantly higher in LBBC than in the other breast tumor subtypes." (PMID 36393855, 2022). "With regard to activation of the canonical Wnt pathway, we observed that RSPO3‐driven breast tumors expressed the Wnt/β‐catenin target genes Axin2, Wif1, Znrf3, and Ctnnb1 itself, however at significantly lower levels than their WNT1‐driven counterparts." (PMID 36106661, 2022). "Recently, gpNMB was found to augment WNT-1-mediated breast tumor initiation and growth by enhancing PI3K/AKT/mTOR pathway signaling and B catenin activity." (PMID 34016993, 2021). "We previously reported that MMTV-Wnt1 mice, an established model for studying Wnt signaling in breast tumors, develop two subtypes of tumors by gene expression classification: Wnt1-EarlyEx and Wnt1-LateEx." (PMID 31213486, 2019). "Using candidate-gene approach, we examined the promoter methylation level of AR, ESR1, hTERT, MYC, RASSF1 and WNT1 in 69 male breast tumors and corresponding blood samples, 7 normal breast tissues and 8 normal lymph node samples." (PMID 29731982, 2018). "Antibodies inhibiting the interaction of LRP6 with Wnt1 or Wnt3a decrease breast tumor growth in Wnt1- and Wnt3a-driven xenografts, respectively." (PMID 29854300, 2018). "In contrast to breast tumors from the other models, the metabolic profiles of C3-TAg tumors include pathways that overlap with Wnt1 tumors, including decreased free fatty acids and increased dipeptides, lysolipids, and eicosanoids." (PMID 29619217, 2018). "We observed breast tumor formation in both Prdm14-KO; Wnt-1 and Prdm14flox/flox; Wnt-1 transgenic mice after parturition and lactation." (PMID 28423353, 2017). "Further investigations are required to analyze the interplay of Wnt1/BCL9-2/Pygo2 for the induction of ER+ breast tumors in vivo." (PMID 25149534, 2014). "MMTV-promoter-Wnt1 transgenic mice develop breast tumors composed of both luminal and myoepithelial component and expanded mammary stem cell pools." (PMID 25406066, 2014). "WISP2 has been shown to be strongly expressed in the stroma of breast tumors in Wnt1-transgenic mice." (PMID 19287498, 2009). "It is possible that the rapid effects of steroid hormones leading to sustained proliferation or survival of breast tumor cells proceed by establishing an autocrine loop of EGFR activity that is linked, in part, to Wnt1 production." (PMID 17897439, 2007). "Based on the ability of Wnt1 to activate EGFR and ERK1/2 signaling in the ER+ T47D and MCF-7 breast tumor cells, we examined the effect of Wnt1 treatment on their response to 4-HT." (PMID 17897439, 2007). "Consequently, these cells are the ones that eventually give rise to breast tumors as a result of insertional mutagenesis, where viral enhancer elements end up activating expression from growth promoting genes, such as Wnt1 and Fgf3." (PMID 37243196, 2023). "Furanoallocolchicinoid chitosan is a “smart” Ringsdorf's antitumor drug conjugate that has been found to induce in vitro tubulin reorganization, cell cycle arrest, and more effective inhibition of the tumor cell proliferation in Wnt-1 breast tumor bearing mice." (PMID 30693034, 2018). "The investigation was made from in vivo study of the compound in Wnt-1 breast tumor bearing mice." (PMID 30693034, 2018).
breast tumors (continued). "Additionally, to further confirm whether Wnt1-positive breast tumor cells represent an LEF1-positive subpopulation, we investigated the co-expression of these markers in tumor xenografts." (PMID 26202299, 2015).